GSTM2 (glutathione S-transferase mu 2)
Diseases named in the same sentence as GSTM2 in open-access papers (continued):
Sharing a sentence is not in itself a finding about the gene and the disease.
colon cancer (continued). "Moreover, we explored the probable reasons for the decreasing expression of GSTM2 in colon cancer." (PMID 36263204, 2022). "Therefore, we hypothesized that GSTM2 might play a role in the tumorigenesis of colon cancer." (PMID 36263204, 2022). "Finally, we revealed that the GSTM2 expression was closely related to the immune-related scores of colon cancer and the infiltration ratios of various immune cells, suggesting that GSTM2 might regulate the development of colon cancer by modulating immune microenvironment." (PMID 36263204, 2022). "Furthermore, we also detected GSTM2 level in different grades, T stages, N stages and M stages of colon cancer, and found that the GSTM2 level in tumor cells and lymphocytes decreased with the increase of M stages, suggesting that GSTM2 might be associated with metastasis." (PMID 36263204, 2022). "As we knew that the transcription factors always had a correlated expression with their downstream genes, thus we used the GEPIA database to explore the expression correlation between GSTM2 and CTCF, RAD21, SP1 in colon cancer." (PMID 36263204, 2022). "GSTM1, GSTM2, and GSTM3 were expressed at significantly higher levels in normal tissues than in colon tumor tissues." (PMID 32539715, 2020). "Furthermore, we investigated the GSTM2 protein level using the data set from CPTAC and discovered that the GSTM2 protein expression in colon cancer tissues was also reduced compared to normal colon tissues (n tumor = 97, n normal = 100)." (PMID 36263204, 2022). "As for histological subtypes, the GSTM2 expression was decreased in tumorous tissues of patients with different subtypes of colon cancer versus normal tissues, but there was no statistical difference between each two histological subtypes." (PMID 36263204, 2022). "As for sub-classification, the GSTM2 protein was decreasingly expressed in mucinous and non-mucinous colon cancer tissues versus normal tissues, but there was no statistical difference between each two sub-classifications." (PMID 36263204, 2022). "As for gender, the GSTM2 protein expression in tumor tissues from both male and female colon cancer patients was lower than in normal tissues, while there was no statistical difference in GSTM2 protein expression between male and female patients." (PMID 36263204, 2022). "The results showed that there were significantly negative expression correlations between the GSTM2 expression with the three transcription factors, which suggested CTCF, RAD21, SP1 as potential transcription factors of GSTM2 in colon cancer." (PMID 36263204, 2022).
colorectal cancer (4 papers, 2016 to 2025). A primary or metastatic malignant neoplasm that affects the colon or rectum. "The results revealed that compared with certain cells from normal tissues, GSTM2 expression was statistically reduced in stem cells (p = 0.008), and had a decreasing trend in fibroblasts (p = 0.311) and B cells (p = 0.13) from colorectal cancer tissues." (PMID 36263204, 2022).
Hypertension (4 papers, 2006 to 2023). The presence of chronic increased pressure in the systemic arterial system. "Interestingly, a similar reduction in GSTM2 was identified in the LVs and aortas of 4-, 8-, and 16-week-old spontaneously hypertensive rats, which develop numerous cardiovascular complications, including cardiac hypertrophy and HF before the onset of hypertension." (PMID 38037116, 2023).
ovarian carcinoma (4 papers, 2020 to 2025). A malignant neoplasm originating from the surface ovarian epithelium. "Database analysis of ovarian cancer cells identified that the high expression of GSTM2, -3, and -4 correlates with the decreased expression of immune checkpoint molecules, such as CTLA-4 and TIGIT." (PMID 38791327, 2024). "Thus, the results highlighted the expression of GSTM2, -3, and -4 in promoting immune escape in ovarian cancer." (PMID 38791327, 2024).
steatosis (4 papers, 2012 to 2022). Increased lipid within the cytoplasm of cells. "Moreover, GSTM2 overexpression reversed methionine choline-deficient diet (MCDD)-induced steatosis." (PMID 35388144, 2022). "In our study, hepatic GSTM2 was found to suppress steatosis by inhibiting ASK1-p38/JNK signalling." (PMID 35388144, 2022). "Furthermore, GSTM1 and GSTM2 that are found to be up-regulated in the fibroblasts of the two steatosis patients are known to be induced by oxidative stress." (PMID 22969728, 2012). "Several studies reported that GSTM1, GSTM2, GSTM4 and GSTM5 mRNA levels are suppressed in patients with steatosis and NASH." (PMID 30080863, 2018). "GSTM2, GSTM4, and GSTM5 mRNA levels are expressed at lower levels in patients with steatosis and NASH." (PMID 23346097, 2013). "In contrast to GSTM2, GSTM1, GSTA4, and GPX4 which are up-regulated in the steatosis patients, GSTT1 is found to be down-regulated." (PMID 22969728, 2012).
breast tumors (3 papers, 2021 to 2025). "The expression of the tumor suppressor gene superoxide dismutase 3 (SOD3) and glutathione S-transferase Mu 2 (GSTM2) has been implicated in aggressive, high-grade breast tumors, where promoter hypermethylation is associated with poor survival in patients." (PMID 39908270, 2025). "Glutathione S-transferase Mu 2 (GSTM2) has been identified in aggressive, high-grade breast tumors where promoter hypermethylation is associated with ER/PR-negative status among ductal carcinoma in situ (DCIS) and invasive tissue components." (PMID 37298314, 2023). "The carcinogen metabolism genes, GSTM1, GSTM2, and GSTM4 are also located in this region and our eQTL analysis of breast tumor revealed highly significant associations between rs17024629 and these genes." (PMID 34234117, 2021).
Hepatic steatosis (3 papers, 2022 to 2023). Steatosis is a term used to denote lipid accumulation within hepatocytes. "In the present study, the close association between GSTM2 knockout and hepatic steatosis was examined by using GSTM2-null mice." (PMID 35388144, 2022). "GSTM2 showed a therapeutic effect on hepatic steatosis, providing a potential strategy for the clinical treatment of NAFLD." (PMID 35388144, 2022). "Our study demonstrated that the hepatic phase II DME, GSTM2, was involved in the development of hepatic steatosis." (PMID 35388144, 2022). "Although GSTM2 was up-regulated in mice with hepatic steatosis, we also overexpressed this protein in mouse model fed with MCDD." (PMID 35388144, 2022). "They show that GSTM2 is a negative regulator of hepatic steatosis via both detoxification/antioxidant and inhibition of ASK1-p38/JNK signalling, which sheds light on its potential as a therapeutic target." (PMID 35388144, 2022). "More importantly, we showed that overexpression GSTM2 had a therapeutic effect on hepatic steatosis." (PMID 35388144, 2022). "To investigate the function of GSTM2 in the progression of hepatic steatosis, we generated a GSTM2 knockout (GSTM2 KO) mouse." (PMID 35388144, 2022). "We demonstrated that GSTM2 suppressed the progression of hepatic steatosis by inhibiting ASK1-p38/JNK signalling." (PMID 35388144, 2022). "Knockout and overexpression of GSTM2 in a mouse model revealed its regulatory function in the development of hepatic steatosis." (PMID 35388144, 2022). "Although both GSTM2-overexpressing mice and control mice showed good recovery of hepatic steatosis at 2 weeks, GSTM2-overexpressing mice showed lower hepatic fat content at 1 week." (PMID 35388144, 2022). "We then investigated whether GS-4997 treatment could rescue the hepatic steatosis induced by GSTM2 knockout." (PMID 35388144, 2022). "Therefore, we identified GSTM2 as an important negative regulator in progression of hepatic steatosis via both its detoxification/antioxidant and inhibition of ASK1-p38/JNK signalling." (PMID 35388144, 2022). "As expected, GSTM2 overexpression promoted the recovery of hepatic steatosis compared to control." (PMID 35388144, 2022). "Moreover, GSTM2 inhibits hepatic steatosis by affecting the capability to detoxify and function as an antioxidant." (PMID 35388144, 2022). "Here, we showed that GSTM2 negatively regulated hepatic steatosis." (PMID 35388144, 2022). "In summary, we identified GSTM2 as a protective factor against hepatic steatosis." (PMID 35388144, 2022). "GSTM2 was highly up-regulated in hepatic steatosis tissues and high-fat diet (HFD) fed mice." (PMID 35388144, 2022). "The rescue experiment suggests that GSTM2 may be a useful therapeutic target for hepatic steatosis." (PMID 35388144, 2022). "Thus, we identified GSTM2 as an important negative regulator in hepatic steatosis progress." (PMID 35388144, 2022). "Cellular repressor of E1A-stimulated genes (CREG) and glutathione S-transferase Mu 2 (GSTM2) inhibits the phosphorylation of ASK1 to block its subsequent downstream signaling, thereby improving insulin resistance and hepatic steatosis." (PMID 37063264, 2023). "Control mice showed significant hepatic steatosis after 1 week of MCDD feeding, whereas mice with GSTM2 overexpression showed this effect at 4 weeks." (PMID 35388144, 2022). "Although GSTM2 overexpression did not block the development of hepatic steatosis, it delayed the progression and reduced lipid accumulation and fibrosis progression." (PMID 35388144, 2022).
bladder cancer (2 papers, 2016 to 2023). "In a global DNA methylation analysis of treatment-naïve bladder cancer patients, the DNA methylation in the GSTM2 and GSTM3 promoter was found to be higher in invasive tumors than in non-invasive types." (PMID 27404495, 2016).
diabetes mellitus (2 papers, 2006 to 2015). A metabolic disorder characterized by abnormally high blood sugar levels due to diminished production of insulin or insulin resistance/desensitization. "Eleven genes in the Glutathione metabolism pathway (Gpx7, Gss, Gsta3, Gstm2, Gstm5, Gstm7, Gsto1, Gstp1, Gstt1, Gstt2 and Mgst2) were observed in type 2 diabetes mellitus." (PMID 25788156, 2015).
glomerulonephritis (2 papers, 2014 to 2022). A renal disorder characterized by damage in the glomeruli. "Using the anti-glomerular basement membrane antibody-induced glomerulonephritis (anti-GBM-GN) mouse model, we found that increased expression of glutathione S-transferase Mu 2 (GSTM2) was related to reduced renal damage caused by anti-GBM antibodies." (PMID 24480247, 2014). "Interestingly, in a previous study glomerulonephritis was treated by injecting GSTM2-transduced mesenchymal stem cells." (PMID 35388144, 2022).
meningioma (2 papers, 2015 to 2024). A generally slow growing tumor attached to the dura mater. "This also aligns with the observation that GSTM1- meningiomas had significantly lower GSTM2 expression versus GSTM1+ meningiomas." (PMID 39726707, 2024). "GSTM1 hemizygous non-recurrent meningiomas either had two GSTM2 alleles or were hemizygous for GSTM2, where loss of a GSTM1 copy was inherited (variant C) or lost due to somatic chr1p deletion (variant D)." (PMID 39726707, 2024). "No meningiomas were homozygous for the wild type allele of GSTM1 (variant E) or had both GSTM1 and GSTM2 somatic deletions (variant F)." (PMID 39726707, 2024). "Four meningiomas were GSTM2 homozygous at a copy number and none were recurrent tumors." (PMID 39726707, 2024).
systemic lupus erythematosus (2 papers, 2025 to 2026). An autoimmune multi-organ disease typically associated with vasculopathy and autoantibody production. "KEGG analysis of GSTM2 demonstrated enrichment in pathways such as ascorbate and aldarate metabolism, olfactory transduction, pentose and glucuronate interconversions, porphyrin and chlorophyll metabolism, and systemic lupus erythematosus." (PMID 40508038, 2025).
cardiac hypertrophy (1 paper, 2023). "However, whether the reduction in GSTM2 in heart tissues during the progression of cardiac hypertrophy and HF is related to AhR and the underlying mechanism need to be further investigated in future studies." (PMID 38037116, 2023). "In conclusion, our study establishes a proteomic and transcriptomic map of human HF tissues, highlights the functional importance of GSTM2 in HF progression, and elucidates potential new targets for treatment of cardiac hypertrophy and HF." (PMID 38037116, 2023). "GSTM2 overexpression indeed partly reversed TAC-induced cardiac hypertrophy and collagen deposition." (PMID 38037116, 2023). "Collectively, these results indicate that GSTM2 inhibits cardiomyocyte eccDNA and IFN-I release, which causes macrophage inflammation during the progression of cardiac hypertrophy." (PMID 38037116, 2023). "This suggests that a reduction in GSTM2 in the early stage may be an essential inducer of cardiac hypertrophy and HF." (PMID 38037116, 2023). "Furthermore, GSTM2 overexpression effectively relieved the progression of cardiac hypertrophy in a transverse aortic constriction (TAC) surgery-induced HF mouse model." (PMID 38037116, 2023). "Furthermore, overexpression of GSTM2 efficiently alleviated cardiac hypertrophy and improved heart function by inhibiting DNA damage, eccDNA production, and IFN-I release by cardiomyocytes and suppressing macrophage inflammation." (PMID 38037116, 2023). "We suspected that GSTM2 participated in cardiac hypertrophy progression." (PMID 38037116, 2023). "In addition, we found that GSTM2, which is a detoxification enzymes, was significantly decreased in HF samples, and GSTM2 in cardiomyocytes inhibited DNA damage and eccDNA production, thereby alleviating macrophage activation and inflammation and eventually ameliorating cardiac hypertrophy." (PMID 38037116, 2023).
cholestasis (1 paper, 2015). Impairment of the bile flow caused by obstruction within the liver, or outside the liver in the bile duct system. "Hepatic mRNA levels of GSTM1, GSTM2, and GSTM4 in patients with cholestasis were decreased to 38%, 46%, and 43% of control, respectively (p<0.05 for all), while GSTM3 and GSTM4 mRNA levels were not significantly changed." (PMID 25798860, 2015).
Depression (1 paper, 2025). "Although previous studies have reported associations between BHLHE41/GSTM2 and both depression and BC, this research is the first to focus on their regulatory roles through the immune system and MAPK pathway." (PMID 40508038, 2025). "Overall, BHLHE41, EPCAM, and GSTM2 consistently suggested their potential as reliable mechanism-associated genes for Depression and BC, with AUC values exceeding 0.7 across both training and validation datasets." (PMID 40508038, 2025). "The literature mining analysis revealed that BHLHE41 and GSTM2 have been previously implicated in both Depression and BC pathogenesis, while EPCAM has been primarily associated with BC." (PMID 40508038, 2025). "Additional analyses identified consistent negative correlations between BHLHE41 and activated dendritic cells (for Depression: p < 0.05; for BC: p < 0.01), EpCAM and immature B cells (for Depression: p < 0.05; for BC: p < 0.01), and GSTM2 and γδ T cells (p < 0.05) across both datasets." (PMID 40508038, 2025). "In the Depression-GSE76826 dataset, the area under the curve (AUC) values were BHLHE41 (0.8333), EPCAM (0.7500), ADH4 (0.7500), GSTM2 (0.8333), and GADD45G (0.8500)." (PMID 40508038, 2025). "Least absolute shrinkage and selection operator (LASSO) regression identified five candidate genes (BHLHE41, EPCAM, ADH4, GSTM2, GADD45G) from the Depression and BC datasets." (PMID 40508038, 2025). "In the Depression-GSE169459 validation set, the AUC values were BHLHE41 (0.8667), EPCAM (0.8667), ADH4 (0.5333), GSTM2 (0.9333), and GADD45G (0.8667)." (PMID 40508038, 2025).
fibrosis (1 paper, 2022). the formation of excess fibrous connective tissue in an organ or tissue in a reparative or reactive process. "In our study, we observed a lower occurrence of fibrosis in GSTM2-overexpressing mice than in control mice." (PMID 35388144, 2022).
Hepatic fibrosis (1 paper, 2022). The presence of excessive fibrous connective tissue in the liver. "Masson staining analysis indicated that control mice had significant hepatic fibrosis compared to mice with GSTM2 overexpression." (PMID 35388144, 2022).
liver cancer (1 paper, 2020). An epithelial or non-epithelial malignant neoplasm that arises from the liver. "GSTM2, a striated muscle-specific isozyme, is highly expressed in mouse liver cancer, and involved in the Wnt/beta-catenin pathway." (PMID 32539715, 2020).
non-small cell lung carcinoma (1 paper, 2021). A group of at least three distinct histological types of lung cancer, including non-small cell squamous cell carcinoma, adenocarcinoma, and large cell carcinoma. "In non-small cell lung cancer, GSTM2 can inhibit cell migration." (PMID 33802702, 2021).
osteosarcoma (1 paper, 2018). A usually aggressive malignant bone-forming mesenchymal neoplasm, predominantly affecting adolescents and young adults. "There is some evidence on differential expression of GSTM class (GSTM2-2 and GSTM4) and GSTP1 in osteosarcoma and soft tissue sarcoma patients." (PMID 30487385, 2018).
ovarian diseases (1 paper, 2023). "In addition, the deregulation of GSTM2 (DNA damage), SFRP1, and BMPR2 (involved in folliculogenesis) has been described in ovarian diseases." (PMID 36982971, 2023).
preeclampsia (1 paper, 2017). Preeclampsia is a hypertensive disorder of pregnancy that is characterized by new-onset hypertension with proteinuria presenting after 20 weeks of gestation, and depending on mild or severe forms may initially present with severe headache, visual disturbances, and hyperreflexia. "In this study, GSTM2 and PRKAR1A were identified to be differentially regulated from the microarray in whole blood from women with preeclampsia and are an intrinsic part of this pathway." (PMID 28130428, 2017).
rectal cancer (1 paper, 2016). A primary or metastatic malignant neoplasm that affects the rectum. "In addition this study showed that the methylation status of GFRA1 or GSTM2 was associated with rectal cancer." (PMID 27566576, 2016). "MS-HRM of two hypermethylated genes (GFRA1 and GSTM2) were conducted to validate an additional 44 pairs of rectal cancer and normal tissue samples." (PMID 27566576, 2016). "We demonstrated that the methylation status of GFRA1 and GSTM2 could be used as potential biomarkers for the screening of rectal cancer." (PMID 27566576, 2016). "The findings of the present study for hypermethylation of GFRA1 and GSTM2 may provide an explanation for their low-expression in rectal cancer." (PMID 27566576, 2016). "Furthermore, the rectal cancer samples showed a significantly greater level of hypermethylated GFRA1 and GSTM2 when compared with the normal samples (P<0.05)." (PMID 27566576, 2016).
type 1 diabetes (1 paper, 2022). "Low expression of GSTM2/4 decrease ROS metabolism to induce Immunologic dysfunction in type 1 diabetes." (PMID 35965498, 2022).